PAK5 (p21 (RAC1) activated kinase 5)
Diseases named in the same sentence as PAK5 in open-access papers (continued):
Sharing a sentence is not in itself a finding about the gene and the disease.
tumor (26 papers, 2014 to 2025). "Additionally, the role of structural variants in PAK1 and the potential tumor‐suppressor functions of PAK5 and PAK6 represent important areas for future exploration." (PMID 39756822, 2025). "Furthermore, the PAK5 serine-rich domain shares 75% homology with other group II PAKs and mutations localized to this region are observed across multiple tumor datasets deposited in cBioPortal." (PMID 29875996, 2018). "Consistent with our in vitro results, specific overexpression of PAK5 significantly alleviated the inhibitory effects of trastuzumab on SK-BR-3 tumor growth, evidenced by a significant increment of tumor size and weight as compared to the FLAG control." (PMID 40258843, 2025). "Immunohistochemical results from tumor and corresponding para-tumor tissues of 273 HCC patients showed that PAK5 was overexpressed in tumor tissues and strongly correlated with tumor progression and worse prognosis of HCC patients." (PMID 36672500, 2023). "Gene silencing of PAK5 attenuated the proliferation and colony formation of HepG2 cells and inhibited the tumor progression in vivo." (PMID 36672500, 2023). "We detected a significant increase of PAK5 in tumor tissue compared with adjacent normal tissues from 40 HCC patients by qRT-PCR." (PMID 34340705, 2021). "Previous studies from our lab and others’ have shown that PAK5 expression augmented in the tumor cells and promoted resistance of antineoplastic drugs." (PMID 34340705, 2021). "PAK5 has currently been shown to be involved in the regulation of cytoskeleton changes, antiapoptosis, and proliferation in tumor cells." (PMID 30245957, 2018). "Ever since its identification in brain neuronal cells, mounting evidence has regarded PAK5 as an important mediator of tumor progression." (PMID 30245957, 2018). "Major signal pathways of PAK5 have been found in tumor progression, which include the regulation of cytoskeleton changes, anti-apoptosis and proliferation in tumor cells." (PMID 29041983, 2017). "In addition, PAK5-mediated signaling pathways such as PAK5-Egr1-MMP2 are involved in tumor cell migration and invasion." (PMID 37627777, 2023). "The results showed that the tumor tissue group (T) possessed higher expression levels of PAK5 protein than normal adjacent tissue group (N), and the miR-106a-5p levels were inversely correlated with PAK5 expression levels (n=30, r=−0.425, P=0.0191, Pearson’s correlation)." (PMID 29072688, 2017). "In addition, PAK5 regulate cytoskeleton remodeling in tumor cell through either stabilizing microtubules by PAK5-MARKK-MARK-tau cascade or facilitating dynamic changes of actin by inducing the formation of filopodia, dissolving stress fibers and focal adhesions." (PMID 29041983, 2017). "Our data provides a comprehensive comparison of DepMap dependency scores for PAK1, PAK2, PAK3, PAK4, PAK5, and PAK6, based on CRISPR analysis of 1100 tumor cell lines and RNAi analysis of 711 cell lines." (PMID 39756822, 2025). "There was mRNAs downregulation of tumor suppressors such as SH3BP4 and DNPEP, which influence oncogenesis via the amino acid-induced TOR signaling and PAK5–DNPEP–USP4 pathway, respectively." (PMID 36354672, 2022).
PAK5 also shares sentences with these, for which no sentence is quoted: osteosarcoma (5 papers); hyperlipidemia (3); acute myeloid leukemia (2); autism (2); bladder cancer (2); cervical cancer (2); glioblastoma (2); prostate tumor (2); psychosis (2); adenoma (1); angiosarcoma (1); basal cell carcinoma (1); bipolar I disorder (1); colon adenocarcinoma (1); colorectal adenocarcinoma (1); endometrial cancer (1); esophageal cancer (1); intimal sarcoma (1); leukemia (1); lymph node metastasis (1); metabolic syndrome (1); non-small cell lung carcinoma (1); Obesity (1); psychiatric disorder (1); schizophrenia (1); stomach cancer (1).